BTN1A1 (butyrophilin subfamily 1 member A1)
Description:
May function in the secretion of milk-fat droplets. May act as a specific membrane-associated receptor for the association of cytoplasmic droplets with the apical plasma membrane (By similarity). Inhibits the proliferation of CD4 and CD8 T-cells activated by anti-CD3 antibodies, T-cell metabolism and IL2 and IFNG secretion (By similarity).
Synonyms: BT; BTN; BTN1
Tractability: Antibody: its Gene Ontology location is reachable by antibodies, with high confidence; UniProt places it where antibodies can reach, with medium confidence; UniProt predicts a signal peptide or a membrane-spanning region.
Gene: Protein-coding gene on chromosome 6 (26,500,303 to 26,510,425, forward strand). Ensembl gene ENSG00000124557.
Subcellular location: Membrane; Secreted
Pathways (Reactome):
Immune System: Butyrophilin (BTN) family interactions
Gene Ontology:
Molecular function: protein binding; signaling receptor activity; signaling receptor binding
Biological process: regulation of cytokine production; T cell receptor signaling pathway
Cellular component: extracellular region; external side of plasma membrane; plasma membrane; membrane
Genetic constraint (gnomAD): Loss-of-function variants: 27 observed, 34.6 expected, observed/expected ratio (o/e) 0.78, 90% interval 0.57 to 1.08. The upper end of that interval is the gene's LOEUF score, 1.08, which puts it in group 4 of 6, group 1 being the genes least tolerant of losing a copy. Missense variants: 558 observed, 695.87 expected, observed/expected ratio (o/e) 0.8, 90% interval 0.75 to 0.86. Synonymous variants: 235 observed, 274.99 expected, observed/expected ratio (o/e) 0.85, 90% interval 0.77 to 0.95.
Homologues: Orthologues: chimpanzee BTN1A1 (99% identical), macaque BTN1A1 (96% identical), pig BTN1A1 (83% identical), rabbit BTN1A1 (81% identical), dog BTN1A1 (79% identical), mouse Btn1a1 (74% identical), rat Btn1a1 (74% identical), guinea pig BTN1A1 (68% identical). Paralogues in human: BTN3A3 (48% identical), BTN2A2 (47% identical), BTN2A1 (45% identical), BTN3A1 (45% identical), BTNL9 (38% identical), ERMAP (33% identical), BTNL3 (31% identical), BTNL8 (30% identical), BTNL2 (28% identical), BTN3A2 (27% identical), CD276 (18% identical), MOG (16% identical), and 3 more.
Diseases named in the same sentence as BTN1A1 in open-access papers:
BTN1A1 is named in the same sentence as 26 diseases in open-access papers, as found by Europe PMC text mining. Sharing a sentence is not in itself a finding about the gene and the disease. The quoted sentences say what the papers report.
breast carcinoma (3 papers, 2020 to 2025). "In human breast cancer, high expression levels of KRT10, HECTD3, NSD3, and STOML2 were associated with unfavorable outcomes, whereas high BTN1A1 expression was linked to a better prognosis." (PMID 40839607, 2025). "While, other phosphoproteins (e.g., BTN1A1, KRT10, HECTD3, NSD3, and STOML2) were associated with human breast cancer prognosis." (PMID 40839607, 2025). "High BTN1A1 expression was correlated with better overall survival in breast cancer." (PMID 40839607, 2025).
follicular lymphoma (1 paper, 2025). Follicular lymphoma is a form of non-Hodgkin lymphoma characterized by a proliferation of B cells whose nodular structure of follicular architecture is preserved. "There were 58 clinic traits related to the BTN1A1, of which 6 phenotypes (schizophrenia, subacute thyroiditis, thyroiditis, and follicular lymphoma) showed positive association." (PMID 40355193, 2025).
glioma (1 paper, 2022). A benign or malignant brain and spinal cord tumor that arises from glial cells (astrocytes, oligodendrocytes, ependymal cells). "Because the basal expression levels of BTN1A1, BTNL2, BTNL3, and BTNL8 were relatively low, in further analysis, we only focused on the expression of BTN2/3 subfamilies in pan-gliomas." (PMID 36033440, 2022).
multiple sclerosis (1 paper, 2025). A progressive autoimmune disorder affecting the central nervous system resulting in demyelination. "On the other hand, antibody cross-reactivity between Btn1a1 and Myelin Oligodendrocyte Glycoprotein is implicated in Multiple Sclerosis 27,28." (PMID 40791429, 2025).
myeloma (1 paper, 2022). "BTN1A1 codes a protein related to the B7 family of costimulatory molecules and was significantly downregulated in myeloma patients, compared to HDs and MGUS." (PMID 35800053, 2022). "On the other hand, immunoglobulin heavy constant mu (IGHM) and butyrophilin subfamily 1 member A1 (BTN1A1) were downregulated in myeloma patients (top)." (PMID 35800053, 2022). "Our findings show that EV-derived proteins (PDIA3, BTN1A1, APRIL) and complement-associated proteins could be further explored in myeloma, as biomarkers across disease natural history and as potential new drug targets that could be monitored by PB sampling." (PMID 35800053, 2022). "We report a set of PB EV-proteins (PDIA3, C4BPA, BTN1A1, and TNFSF13) with a new biomarker potential for myeloma patient outcomes." (PMID 35800053, 2022).
sarcoidosis (1 paper, 2024). Sarcoidosis is a multisystemic disorder of unknown cause characterized by the formation of immune granulomas in involved organs. "Both BTN1A1 and BTNL2 have been reported to exert immunomodulatory functions and foster immune evasion when expressed on cancer cells and BTNL2 has been associated with immunological disorders such as sarcoidosis." (PMID 39035010, 2024).
subacute thyroiditis (1 paper, 2025). Self-limited inflammation of the thyroid gland characterized by the presence of multinucleated giant cells. "For instance, BTN1A1 would increase the subacute thyroiditis risk (OR, 3.28; 95% CI, 2.30–4.69; PFDR = 2.89 × 10−8)." (PMID 40355193, 2025).
thyroiditis (1 paper, 2025). Inflammation of the thyroid gland. "Additionally, BTN1A1 was related to the increased risk of thyroiditis (OR, 1.93; 95% CI, 1.52–4.69; PFDR = 2.01 × 10−5)." (PMID 40355193, 2025).
tumor (13 papers, 2018 to 2025). "The expression of several butyrophilin (BTN) and butyrophilin-like (BTNL) molecules was significantly altered by inflammation, including BTN1A1, BTN2A2, BTN3A3, and BTNL831, and associated with tumor development." (PMID 37369724, 2023).
cancer (10 papers, 2016 to 2025). A tumor composed of atypical neoplastic, often pleomorphic cells that invade other tissues. "Furthermore, proteins, such as butyrophilin subfamily 1 member A1, keratin, type I cytoskeletal 10, HECT domain E3 ubiquitin protein ligase 3, nuclear receptor binding SET domain protein 3, and stomatin-like 2, were identified and implicated in cancer progression and prognosis." (PMID 40839607, 2025).
infection (2 papers, 2020). The state of being infected such as from the introduction of a foreign agent such as serum, vaccine, antigenic substance or organism. "Lentivirus-mediated infection of the Cas9/sgRNA expression vector into BMEC resulted in production of a homozygous clone BTN1A1(−/−)." (PMID 32637097, 2020).
BTN1A1 also shares sentences with these, for which no sentence is quoted: autoimmune disease (2 papers); colon tumors (2); coronary heart disease (2); ovarian carcinoma (2); asthma (1); autism (1); colon cancer (1); intestinal tumors (1); irritable bowel syndrome (1); lung carcinoma (1); mastitis (1); measles (1); schizophrenia (1); ulcerative colitis (1); virus infection (1).